APC (APC regulator of Wnt signaling pathway)
Diseases named in the same sentence as APC in open-access papers (continued):
Sharing a sentence is not in itself a finding about the gene and the disease.
ovarian epithelial tumor (2 papers, 2011 to 2014). A benign, borderline, or malignant tumor that originates from the surface epithelium of the ovary. "In a previous report, it was observed that combined deletion of APC and PTEN causes formation of ovarian epithelial tumors accompanied by loss of E-cadherin expression and appearance of mesenchymal like-cells suggesting EMT." (PMID 21695255, 2011).
ovarian serous adenocarcinoma (2 papers, 2006 to 2015). An adenocarcinoma that arises from the ovary and is characterized by the presence of malignant epithelial cells that, in well differentiated tumors, resemble the epithelium of the fallopian tube or, in poorly differentiated tumors, show anaplastic features and marked nuclear atypia. "Similar results were found when conducting ChIP on high-grade serous ovarian cancer cells (OVCAR3), with significant ARID3B binding found to Wnt5a, RIPK, BTC, and APC." (PMID 26121572, 2015). "It has been suggested that downregulated expression of APC or secreted frizzled-related proteins (SFRPs) inactivation by methylation could explain, at least partially, why ovarian serous adenocarcinomas show increased β-catenin protein expression in spite of the absence of gene mutation." (PMID 16479254, 2006).
pancreatic NET (2 papers, 2020 to 2023). "Hallmarks of NET G1/G2 are loss of chromosome 18, inactivation of CDKN1/APC, and gain of chromosomes 4, 5, and 14 in NET of the small intestine and inactivation of MEN1/chromosome 11, DAXX/ATR, and PTEN/TSC2 in pancreatic NET." (PMID 33228231, 2020).
Parkinson disease (2 papers, 2022 to 2024). A progressive degenerative disorder of the central nervous system characterized by loss of dopamine producing neurons in the substantia nigra and the presence of Lewy bodies in the substantia nigra and locus coeruleus. "Among the top predictions in zebrafish are genes associated with human diseases including Parkinson’s disease (PARK7), cancer (APC, a known tumor suppresion gene) and kidney failure (PKD2)." (PMID 36158574, 2022). "Finally, Parkin, an E3 ubiquitin ligase involved in the development of Parkinson’s disease, binds to both Cdh1 and Cdc20 independently, but not to core APC/C components, and this association regulates APC/C substrates and the cell cycle." (PMID 38932933, 2024).
rectal NETs (2 papers, 2023).
rectum adenoma (2 papers, 2021 to 2025). An adenoma that arises from the rectum. "Furthermore, a rectum adenoma showed two distinct APC variants." (PMID 40956995, 2025). "FAP patients develop hundreds of colon and rectum adenomas since young age, and CRC in untreated patients, due to a germline loss of function mutation in the APC gene." (PMID 33901189, 2021).
renal fibrosis (2 papers, 2024). A final common manifestation of a wide variety of chronic kidney diseases characterized by glomerulosclerosis and tubulointerstitial fibrosis. "Further investigations into the expression of APC and ZBTB2 in M2 macrophages hold promise for providing fresh insights into the mechanisms underlying renal fibrosis and facilitating the development of innovative therapeutic approaches to combat this disease." (PMID 39328595, 2024). "In addition, the expression of APC and ZBTB2 was significantly decreased in M2 macrophages from uremic patients, and APC and ZBTB2 were identified as potential renal fibrosis biomarkers associated with M2 macrophage infiltration." (PMID 39328595, 2024). "However, in renal fibrosis, Wnt molecules bind to cell membrane surface receptors, disrupting the formation of the APC-Axin-GSK-3β complex." (PMID 39325739, 2024). "Therefore, in delaying renal fibrosis, we speculate that APC and ZBTB2 may be potential therapeutic targets." (PMID 39328595, 2024). "Therefore, we hypothesized that the downregulation of APC could have mediated the infiltration of M2 macrophages through the activation of the Wnt signaling pathway, thereby promoting the progression of renal fibrosis." (PMID 39328595, 2024). "We hypothesize that APC and ZBTB2 are closely associated with M2 macrophage infiltration, and uncovering the role of APC and ABTB2 in M2 macrophage infiltration may unravel the physiopathological mechanisms underlying the development of renal fibrosis." (PMID 39328595, 2024). "Additional in vitro and in vivo studies are necessary to investigate the specific mechanisms by which APC and ZBTB2 affect M2 macrophage infiltration in renal fibrosis." (PMID 39328595, 2024). "First, the study is retrospective; in-depth studies are needed to clarify the role of APC and ZBTB2 in renal fibrosis." (PMID 39328595, 2024). "This reduced expression of APC and ZBTB2 in M2 macrophages serves as a significant indicator for the presence of renal fibrosis." (PMID 39328595, 2024). "Our study showed that the expression of APC and ZBTB2 was closely correlated with the abundance of M2 macrophages, suggesting that APC and ZBTB2 may exacerbate renal fibrosis through infiltration of M2 macrophages." (PMID 39328595, 2024). "In conclusion, these findings imply that APC and ZBTB2 may contribute to the progression of renal fibrosis by mediating M2 macrophage infiltration." (PMID 39328595, 2024). "Unfortunately, there are no relevant studies to investigate the role of APC in renal fibrosis." (PMID 39328595, 2024).
small bowel cancer (2 papers, 2019 to 2021).
small intestinal adenoma (2 papers, 2018 to 2022). "For this purpose, a commercially available probe (IntegriSense), recognizing integrin αvβ3, was injected in APC+/min mice bearing small intestinal adenomas or CRC: FMT analysis allowed a specific tumor detection, further confirmed by subsequent ex vivo imaging or conventional histology." (PMID 30140377, 2018).
small intestinal cancer (2 papers, 2015 to 2024). "Why do humans not get small intestinal cancer with β-catenin exon 3 mutations rather than CRC with APC mutations?" (PMID 26240067, 2015).
Thrombocytopenia (2 papers, 2016 to 2025). A reduction in the number of circulating thrombocytes. "In this patient, the MYH9 variant likely explains thrombocytopenia; the APC mutation, possibly incidental, may have broader immunological effects, as suggested by studies on APC mutations affecting T-cell function." (PMID 40941697, 2025). "Furthermore, aPS is moderately associated with both canine immune thrombocytopenia and severe thrombocytopenia negative for aPLT, whereas aβ2GPI, and aPC are moderately relevant to canine immune thrombocytopenia." (PMID 27297331, 2016). "In the future, it would be interesting to explore whether aCL, aβ2GPI, aPC, and aPS poses differential risks under the presence or absence of aPLT in less severe thrombocytopenia or even mild thrombocytopenia." (PMID 27297331, 2016).
tubulovillous adenoma (2 papers, 2021 to 2026). An epithelial neoplasm morphologically characterized by the presence of a villous and a tubular architectural pattern. "Conventional tubular or tubulovillous adenomas (TVAs) are ligand independent, and their tumor-initiating APC or CTNNB1 mutations likely occur in stem cells." (PMID 34788095, 2021).
urothelial bladder cancer (2 papers, 2014 to 2023). "Our results suggest that epigenetic silencing of RASSF1A, APC and MGMT genes is strongly associated with invasive high grade urothelial bladder cancer." (PMID 24790823, 2014). "As an interesting finding hypermethylation of APC gene promoter was more prominent in invasive high grade urothelial bladder cancer as compared to noninvasive low grade one which is also in line with the previous studies correlating APC methylation with tumor grade, stage and muscle invasion." (PMID 24790823, 2014). "NIM was found to be higher for RASSF1A, APC and MGMT in muscle invasive high grade urothelial bladder cancer as compared to the non muscle invasive low grade cancer." (PMID 24790823, 2014). "When the mean normalized index of methylation of the genes was compared between non- muscle invasive low grade and muscle invasive high grade urothelial bladder cancer, the degree of hypermethylation was more prominent in the muscle invasive high grade group for RASSF1A, APC and MGMT (p < 0.001)." (PMID 24790823, 2014).
viral infection (2 papers, 2022 to 2024). "Human cytomegalovirus viral infection targets APC4, APC5, and APC1 for degradation, resulting in loss of APC/C activity." (PMID 38932933, 2024). "The higher maximum in [I] for the 80% APC activities was attributed to a raise in viral infection flux that was indirectly mediated by the accumulated effects of reduction in each reaction rate related to APC activities." (PMID 35813874, 2022).
Adamantinomatous Craniopharyngioma (1 paper, 2021). A craniopharyngioma consisting of broad strands, cords and bridges of a multistratified squamous epithelium with peripheral palisading of nuclei. "In this report, we describe the first case, to our knowledge, of adamantinomatous craniopharyngioma arising from somatic loss of APC in the absence of germline mutations or a CTNNB1 mutation." (PMID 34549183, 2021). "Taken together, this case demonstrates that adamantinomatous craniopharyngiomas, typically driven by proto-oncogenic CTNNB1 mutations, may also arise independently from loss of the tumor suppressor gene APC, leading to similar downstream constitutive activation of the Wnt signaling pathway." (PMID 34549183, 2021).
adenosarcoma (1 paper, 2017). A low grade malignant neoplasm characterized by the presence of a benign epithelial component (tubular and cleft-like glands) and a low grade sarcomatous component that contains varying amounts of fibrous and smooth muscle tissues. "In addition, the Wnt signaling pathway was significantly altered in adenosarcomas, which harbored, among other alterations in Wnt pathway‐related genes, homozygous deletions of APC (1/19, 5%) and SMARCA4 (1/19, 5%) and nonsynonymous mutations affecting AXIN1 (1/19, 5%) and AXIN2 (1/19, 5%)." (PMID 28267263, 2017).
AIDS (1 paper, 2021). A syndrome resulting from the acquired deficiency of cellular immunity caused by the human immunodeficiency virus (HIV). "Considering that the age density of AIDS patients with different transmission routes varied, APC models were also established for each transmission routes." (PMID 34090398, 2021).
anaplastic ependymoma (1 paper, 2023). Anaplastic ependymoma is a rare, malignant type of ependymoma that most often arises in the supratentorial region of the brain of children and young adults and that manifests with variable symptoms including headaches, nausea, vision impairment, memory loss and difficulty walking. "Notably, synonymous variants found in this tumor were detected in other tumors, such as APC (rs41115) variant in MPE, FGFR3 (rs7688609), PDGFRA (rs1873778), and RET (rs1800861) in anaplastic ependymoma Grade III tumor, a-CPP, and myxo-papillary ependymoma (MPE) tumors." (PMID 37273678, 2023).
aneuploidy (1 paper, 2016). Chromosomal disorder consisting of the presence a chromosomal abnormality in which there is an addition or loss of chromosomes within a set. "The role of APC herein is less established, although some studies have described that loss of APC function was associated with aneuploidy." (PMID 27729614, 2016).
aplastic anemia (1 paper, 2017). Anemia resulting from bone marrow failure (aplastic or hypoplastic bone marrow). "CD34+ cells were markedly decreased in the bone marrow and Anapc2-expression in the residual CD34+ cells was undetectable, suggesting that APC/C was deficient and might have a relationship with the pathogenesis of aplastic anemia." (PMID 28968996, 2017).
Arterial thrombosis (1 paper, 2008). The formation of a blood clot inside an artery. "In the present study, the potential antithrombotic effects of this APC variant, and of a variant APC that is additionally mutated in the serine protease domain, have been evaluated in a blind randomized study in a rat model of arterial thrombosis." (PMID 18957140, 2008). "In conclusion, administration of human APC variants having enhanced anticoagulant efficacy together with human PS in a rat model of arterial thrombosis did not give an efficient antithrombotic effect." (PMID 18957140, 2008).
asthma (1 paper, 2020). "We examine the clinical implications of APC dysregulation in the airways on asthma and tuberculosis, two chronic diseases that are the major cause of illness and death in the developed and developing world." (PMID 32714552, 2020).
autism spectrum disorder (1 paper, 2020). A spectrum of developmental disorders that includes autism, and Asperger syndrome. "Evidence for a potential etiologic role of APC protein in neurodevelopmental disorders arises from human studies examining the association of APC gene polymorphisms and autism spectrum disorders." (PMID 32123549, 2020). "In our Polyposis Registry, we have several patients with either mutations and/or deletion of the APC gene who are also diagnosed with autism spectrum disorder." (PMID 32123549, 2020).
benign meningioma (1 paper, 2016). A grade I, slowly growing meningioma. "The observed genetic changes of the APC gene were dispersed among different types of benign meningioma, indicating that APC is not likely to be the first event in the advancement of this tumour." (PMID 27429002, 2016).
benign parathyroid tumours (1 paper, 2010). "In our tumour panel, hypermethylation of the APC promoter 1A was found in the majority of benign parathyroid tumours, as well as in one familial HRPT2 related case." (PMID 20208994, 2010).
benign thyroid tumors (1 paper, 2017). "A study of mutations in Beta-catenin and APC genes in PTC, FTC and benign thyroid tumors suggested that mutations in these genes are rare and that the activation of the Wnt signaling pathway may not contribute to pathogenesis in human PTC and FTC." (PMID 28410400, 2017).
Burkitt lymphoma (1 paper, 2016). A rare form of malignant mature B-cell non-Hodgkin lymphoma. "In addition, a heterozygous single-nucleotide polymorphism (SNP, dbSNP# rs1801166) in APC was found in the ST486 Burkitt lymphoma cell line (c.3949G>C (p.Glu1317Gln))." (PMID 26999048, 2016). "Furthermore, an APC variant found in the background Burkitt lymphoma cell line (ST486) was suppressed in the xMD specimen, supporting the improved specificity of the xMD technique." (PMID 26999048, 2016).
cardiac hypertrophy (1 paper, 2016). "GSK-3β is detected in two states in the cytoplasm: in a free form or in a complex with APC/Axin to regulate the activity of the canonical Wnt/β-catenin pathway, which is associated with cell cycle control, survival, and cardiac hypertrophy." (PMID 27977752, 2016).
cataract (1 paper, 2023). Partial or complete opacity of the crystalline lens of one or both eyes that decreases visual acuity and eventually results in blindness. "RTS1 individuals who present the distinctive sign of bilateral cataracts have decreased APC levels and their synchronized fibroblasts in vitro undergo a defective cell cycle with a longer interphase." (PMID 36835439, 2023).
cerebral malaria (1 paper, 2017). A sequestration of Plasmodium falciparum in the brain, which can cause coma and/or seizures. "It has been postulated that EPCR binding P. falciparum parasites contribute to cerebral malaria brain swelling by inhibiting the APC-EPCR interaction (29, 38, –, 40)." (PMID 28101534, 2017).
cervical tumors (1 paper, 2015). "Several human genes that encode functional inhibitors of the Wnt pathway have been reported to be methylated in cervical tumors including WIF1, CDH1, FHIT, APC, the SLIT2/ROBO family and the SRFP family." (PMID 25826459, 2015).
chromophobe renal cell carcinoma (1 paper, 2024). Chromophobe renal cell carcinoma is a rare subtype of renal cell carcinoma, originating from the intercalating cells of the collecting ducts and macroscopically manifesting as a well-circumscribed, highly lobulated, solid tumor that is usually diagnosed at an early stage. "Transcriptional activation and apoptosis have also been reported in CHRCC metastatic chromophobe renal cell carcinoma with APC mutation." (PMID 38730456, 2024).
chronic hepatitis (1 paper, 2007). An active inflammatory process affecting the liver for more than six months. "Interestingly, APC gene was commonly methylated in fully normal liver tissues (88.2%, 15 of 17), and reduced methylation frequency was detected in cirrhotic liver and/or tissue in chronic hepatitis (21.6%, 11 of 51)." (PMID 17968429, 2007).
chronic hepatitis C (1 paper, 2013). "In chronic hepatitis C patients, methylation frequencies in many TSGs, such as RASSF1, CDKN2A, APC, and RUNX3, were associated with shorter time-to-HCC occurrence." (PMID 24330717, 2013).
colon epithelial tumors (1 paper, 2020). "However, the majority of APC mutant colon epithelial tumors are benign and never progress to CRC, suggesting that other genetic alterations are required for the development of WNT signaling-mutant colon epithelia into CRC." (PMID 32042269, 2020).
congenital muscular dystrophy (1 paper, 2023). A muscular dystrophy that is characterized by diminished muscle tone (hypotonia), progressive muscle weakness and degeneration (atrophy), abnormally fixed joints, spinal rigidity, and delays in reaching motor milestones such as sitting or standing unassisted. "The ability of negamycin to induce PTC readthrough has been confirmed in models of DMD, congenital muscular dystrophy (CMD), CF, and APC tumor suppressor gene." (PMID 37371567, 2023).
craniopharyngioma (1 paper, 2021). A benign, partly cystic, epithelial tumor of the sellar region, presumably derived from Rathke pouch epithelium. "Here, we describe the first case to our knowledge of craniopharyngioma formation, driven by loss of APC function secondary to 2 independent somatic mutations rather than germline pathogenic variants." (PMID 34549183, 2021). "In contrast, only a few reports of craniopharyngiomas, arising from complete loss of APC through a germline and a second-hit somatic mutation and in the absence of CTNNB1 mutations, have been reported to date." (PMID 34549183, 2021). "While this study implicated loss of APC in craniopharyngioma formation, direct causality remained unclear due to the uncertain pathogenicity of the germline APC variant and inability to demonstrate biallelic loss of APC in both patients." (PMID 34549183, 2021). "This study provides evidence that somatic loss of APC can lead to sporadic craniopharyngioma formation and may comprise a subset of adamantinomatous craniopharyngiomas that are otherwise wildtype for CTNNB1." (PMID 34549183, 2021). "Additionally, while it has been suggested that APC-driven craniopharyngiomas may have a predilection for ectopic formation, our case demonstrates that typical, sellar craniopharyngiomas may also arise from loss of APC." (PMID 34549183, 2021). "Additional genetic studies are needed to determine whether significant biological differences exist in APC- vs CTNNB1-driven craniopharyngiomas that may guide further clinical decision making and development of target therapies." (PMID 34549183, 2021). "In adamantinomatous craniopharyngiomas that are wildtype for CTNNB1 in targeted screens, APC sequencing may be considered." (PMID 34549183, 2021).